FIG4 (FIG4 phosphoinositide 5-phosphatase)
Description:
Dual specificity phosphatase component of the PI(3,5)P2 regulatory complex which regulates both the synthesis and turnover of phosphatidylinositol 3,5-bisphosphate (PtdIns(3,5)P2). Catalyzes the dephosphorylation of phosphatidylinositol 3,5-bisphosphate (PtdIns(3,5)P2) to form phosphatidylinositol 3-phosphate. Has serine-protein phosphatase activity acting on PIKfyve to stimulate its lipid kinase activity, its catalytically activity being required for maximal PI(3,5)P2 production. In vitro, hydrolyzes all three D5-phosphorylated polyphosphoinositide and although displaying preferences for PtdIns(3,5)P2, it is capable of hydrolyzing PtdIns(3,4,5)P3 and PtdIns(4,5)P2, at least in vitro.
Synonyms: KIAA0274; SAC3; hSac3; dJ249I4.1; ALS11; CMT4J; BOP; BTOP; YVS
Tractability: Antibody: UniProt places it where antibodies can reach, with high confidence. PROTAC: ubiquitination databases record sites on it; its protein half-life has been measured.
Gene: Protein-coding gene on chromosome 6 (109,690,609 to 109,878,098, forward strand). Ensembl gene ENSG00000112367.
Subcellular location: Endosome membrane
Subcellular location (Human Protein Atlas): Lipid droplets; Vesicles
Pathways (Reactome):
Metabolism: Synthesis of PIPs at the Golgi membrane; Synthesis of PIPs at the early endosome membrane; Synthesis of PIPs at the late endosome membrane
Gene Ontology:
Molecular function: phosphatidylinositol-3,4,5-trisphosphate 5-phosphatase activity; phosphatidylinositol-3,5-bisphosphate 5-phosphatase activity; phosphatidylinositol-4,5-bisphosphate 5-phosphatase activity; protein binding; protein serine/threonine phosphatase activity; phosphatase activity; phosphatidylinositol bisphosphate phosphatase activity; phosphatidylinositol-3-phosphate phosphatase activity; phosphatidylinositol-4-phosphate phosphatase activity
Biological process: 1-phosphatidyl-1D-myo-inositol 3,5-bisphosphate metabolic process; phosphatidylinositol biosynthetic process; phosphatidylinositol dephosphorylation; phosphatidylinositol-3-phosphate biosynthetic process; positive regulation of neuron projection development
Cellular component: endosome membrane; PAS complex; early endosome membrane; Golgi membrane; late endosome membrane; recycling endosome
Genetic constraint (gnomAD): Loss-of-function variants: 61 observed, 78.18 expected, observed/expected ratio (o/e) 0.78, 90% interval 0.63 to 0.97. The upper end of that interval is the gene's LOEUF score, 0.97, which puts it in group 4 of 6, group 1 being the genes least tolerant of losing a copy. Missense variants: 745 observed, 891.88 expected, observed/expected ratio (o/e) 0.84, 90% interval 0.79 to 0.89. Synonymous variants: 277 observed, 309.61 expected, observed/expected ratio (o/e) 0.89, 90% interval 0.81 to 0.99.
Gene-disease validity (ClinGen):
ClinGen rates the evidence that FIG4 causes each of these diseases.
Charcot-Marie-Tooth disease (autosomal recessive): Definitive. An inherited degenerative disorder involving the peripheral nerves.
amyotrophic lateral sclerosis type 11 (autosomal dominant): Limited. Any amyotrophic lateral sclerosis in which the cause of the disease is a mutation in the FIG4 gene.
Homologues: Orthologues: macaque FIG4 (99% identical), chimpanzee FIG4 (98% identical), dog FIG4 (98% identical), rabbit FIG4 (97% identical), mouse Fig4 (95% identical), rat Fig4 (94% identical), pig FIG4 (91% identical), tropical clawed frog FIG4 (84% identical), Drosophila melanogaster FIG4 (41% identical), zebrafish FIG4 (39% identical), Caenorhabditis elegans figo-1 (35% identical). Paralogues in human: INPPL1 (15% identical), SYNJ2 (14% identical), INPP5D (14% identical), SYNJ1 (13% identical), INPP5B (13% identical), INPP5F (13% identical), OCRL (12% identical), INPP5J (10% identical), SACM1L (10% identical), INPP5E (9% identical), INPP5K (7% identical), SH2D1A (2% identical), and 1 more.
Diseases named in the same sentence as FIG4 in open-access papers:
FIG4 is named in the same sentence as 62 diseases in open-access papers, as found by Europe PMC text mining. Sharing a sentence is not in itself a finding about the gene and the disease. The quoted sentences say what the papers report.
amyotrophic lateral sclerosis (17 papers, 2013 to 2025). Amyotrophic lateral sclerosis (ALS) is a neurodegenerative disease characterized by progressive muscular paralysis reflecting degeneration of motor neurons in the primary motor cortex, corticospinal tracts, brainstem and spinal cord. "Although monoallelic variants in the FIG4 gene have been associated with amyotrophic lateral sclerosis (OMIM:612577), this specific variant is prevalent in the general population in the heterozygous state." (PMID 38839988, 2024). "Heterozygous autosomal-dominant FIG4 mutations are associated with amyotrophic lateral sclerosis (ALS)." (PMID 36090855, 2022). "FIG4 mutations lead to neurodegenerative diseases such as Charcot-Marie-Tooth disease and Amyotrophic Lateral Sclerosis (ALS)." (PMID 33536571, 2021). "Lastly, heterozygous FIG4 mutations have been reported to cause amyotrophic lateral sclerosis (ALS; MIM 612577), a progressive disorder associated with motor neuron pathology." (PMID 31413155, 2019). "Haploinsufficiency of FIG4 may also be a risk factor for amyotrophic lateral sclerosis (ALS)." (PMID 25187576, 2015). "Furthermore, as with TRPML1, mutations in the human PIKfyve complex, namely the FIG4 and Vac14 components, lead to neurodegeneration – in this case, including amyotrophic lateral sclerosis (ALS), Charcot–Marie–Tooth disease, and Yunis–Varon syndrome." (PMID 36825945, 2023). "In addition, we (the Meisler group) have identified recessive FIG4 mutations in patients with hereditary peripheral neuropathy (Charcot-Marie-Tooth Disease type 4J) and motor neuron disease (amyotrophic lateral sclerosis, or ALS)." (PMID 24004519, 2013). "Finally, the significance of this complex is highlighted in humans where loss-of-function mutations in FIG4 and VAC14 genes result in severe neurological disorders including Amyotrophic Lateral Sclerosis (ALS), Charcot Marie Tooth Type 4 J and Yunis-Varón Syndrome13,15–18." (PMID 41315403, 2025). "Mutations in the Factor-Induced Gene 4 (FIG4) have been implicated in various neurological disorders, including Charcot-Marie-Tooth disease type 4J (CMT4J), amyotrophic lateral sclerosis (ALS), and Yunis-Varón syndrome." (PMID 39457468, 2024).
neuropathy (10 papers, 2008 to 2025). A disorder affecting the nervous system that manifests with pain, tingling, numbness, and/or muscle weakness. "In contrast, all reported cases of patients with FIG4 mutations who developed parkinsonism also suffered from CMT4J neuropathy." (PMID 39457468, 2024). "Mutations in FIG4 are associated with CMT4J neuropathy characterized by both axonal and myelin damage in peripheral nerve." (PMID 22028665, 2011). "At this stage, sciatic nerves from Mtmr2−/−Fig4−/− double null mice were more severely hypomyelinated than Mtmr2+/+Fig4−/− mice with a higher g-ratio, demonstrating that Mtmr2 loss exacerbates the neuropathy of Mtmr2+/+Fig4−/− mice." (PMID 22028665, 2011). "Notably, biallelic pathogenic variants in the FIG4 gene cause neuropathy, a condition distinct from a brain calcification disorder, which was the diagnostic referral in this case." (PMID 38839988, 2024). "In addition, we found that haploinsufficiency of Fig4 does not ameliorate effects of Mtm1 mutation in muscle, in contrast to a previous report that haploinsufficiency of Fig4 rescues the neuropathy associated with Mtmr2 mutation." (PMID 24004519, 2013). "In addition, most abnormalities associated with Fig4 mutation appears to be secondary to the severe neuropathy documented in plt mice." (PMID 24004519, 2013). "Our findings support the inclusion of FIG4, particularly the I41T mutation, in focused genetic screening for cases with potential autosomal recessive inheritance and/or concomitant unexplained neuropathy or skeletal deformities, as well as a positive family history of various neurological diseases." (PMID 39457468, 2024). "Adding to the phenotypic heterogeneity of FIG4, we review here 12 published cases of CMT4J neuropathy due to FIG4 mutations that also developed parkinsonian symptoms and signs." (PMID 39457468, 2024). "In human, recessive mutations in FIG4 are responsible for the neurodegenerative Yunis-Varón syndrome, familial epilepsy with polymicrogyria, and Charcot-Marie-Tooth type 4J (CMT4J) neuropathy." (PMID 25187576, 2015). "Mice with a recessive mutation in Mtmr2 exhibit peripheral neuropathy, and aspects of this neuropathy are reversed in the setting of Fig4 haploinsufficiency." (PMID 24004519, 2013). "On the basis of the ability of reduced FIG4 levels to rescue aspects of Mtmr2-dependent neuropathy, we evaluated the effect of Fig4 haploinsufficiency on the myopathy of Mtm1-knockout mice." (PMID 24004519, 2013). "Mutations in some phosphoinositide metabolism genes (FIG4, PTEN, MTMR2, and SBF1) also cause neuropathies with conduction slowing and/or CB,26, 27, 28 suggesting a more fundamental role of GPI in the pathophysiology of this inherited neuropathy, independent of the GPI‐APs that are affected." (PMID 39444079, 2025). "Whereas Fig4 haploinsufficiency improves the neuropathy phenotype of Mtmr2 KO mice, Mtmr2 mutation does not appear to positively modulate the Fig4 phenotype (and in fact increases motor neuron loss)." (PMID 31413155, 2019). "The Fig4Floxed/Floxed, P0-Cre and Fig4Floxed/plt, P0-Cre mutants that we generated with conditional ablation of Fig4 in Schwann cells displayed demyelinating features such as myelin debris and degeneration, onion bulbs and decrease of NCV, thus recapitulating demyelination of the CMT4J neuropathy." (PMID 25187576, 2015).
Yunis-Varón syndrome (7 papers, 2015 to 2024). "The lethal multisystem disorder Yunis-Varón Syndrome results from complete loss-of-function of FIG4 or VAC14." (PMID 37363915, 2023). "Complete loss-of-function of FIG4 results in Yunis-Varón Syndrome (OMIM 216340), a lethal multisystem disorder affecting development of the skeleton and nervous system." (PMID 36691351, 2023). "Mutations of FIG4 are responsible for Yunis-Varón syndrome, familial epilepsy with polymicrogyria, and Charcot-Marie-Tooth type 4J neuropathy (CMT4J)." (PMID 25187576, 2015). "The data demonstrate interaction between these two genes, and suggest that inhibition of the kinase PIPK4C2 could be a target for treatment of FIG4 deficiency disorders such as Charcot-Marie-Tooth Type 4J and Yunis-Varón Syndrome." (PMID 36691351, 2023). "Therefore, some variants in FIG4 are related to neurological disorders, such as Charcot-Marie-Tooth disease and Yunis-Varón syndrome." (PMID 36662838, 2023). "Reduction of CLCN7 provides a new target for treatment of FIG4 and VAC14 deficiencies that lack specific therapies, such as Charcot-Marie-Tooth Type 4J and Yunis-Varón syndrome." (PMID 37363915, 2023). "In the FIG4 null disorder Yunis-Varón Syndrome, osteoblast cultures accumulate large vacuoles and patients display multiple skeletal defects including reduced bone density, digital abnormalities and cleidocranial dysplasia, suggesting a defect in bone deposition." (PMID 37363915, 2023).
Charcot-Marie-Tooth disease type 4J (5 papers, 2011 to 2024). Charcot-Marie-Tooth disease, type 4J (CMT4J) belongs to the genetically heterogeneous group of CMT peripheral sensorimotor polyneuropathy diseases. "In humans, mutations in Fig4 are causative of Charcot-Marie-Tooth disease type 4J and are associated with forms of amyotrophic lateral sclerosis." (PMID 23544129, 2013). "Mutations of FIG4 are responsible for Charcot-Marie-Tooth Disease type 4J (OMIM 611228), an atypical, autosomal recessive form of CMT with severe motor dysfunction and rapid progression." (PMID 21655088, 2011). "FIG4 was previously implicated in Charcot-Marie-Tooth disease type 4J (CMT4J)." (PMID 26843957, 2016). "In other words, the myopathic changes described herein may influence disease severity in patients with Charcot-Marie-Tooth disease type 4J and other disorders caused by FIG4 gene mutation." (PMID 24004519, 2013). "This suggests that the neurodegenerative phenotype observed in mice deficient in Fig4 or Vac14, and in Charcot-Marie-Tooth disease type 4J disease in humans, is unlikely to be mediated by apoptosis." (PMID 23544129, 2013).
Charcot-Marie-Tooth disease (4 papers, 2011 to 2023). "The rs121908287 in the FIG4 gene was reported as related to Charcot-Marie-Tooth disease, type 4J (OMIM #609390) when found in compound heterozygosity with a second FIG4 pathogenic variant." (PMID 34125832, 2021). "Slowed nerve conduction secondary to defective myelination is another characteristic of Charcot-Marie-Tooth disease that is reproduced in Fig4 null mice." (PMID 21655088, 2011).
cleidocranial dysplasia (4 papers, 2021 to 2025). "Yunis–Varón syndrome is caused by complete loss-of-function of FIG4 and is characterized by severe neurological anomalies, cleidocranial dysplasia, and digital anomalies." (PMID 40860339, 2025).
Parkinsonism (4 papers, 2015 to 2025). Characteristic neurologic anomaly resulting from degeneration of dopamine-generating cells in the substantia nigra, a region of the midbrain, characterized clinically by shaking, rigidity, slowness of movement and difficulty with walking and gait. "We report rapidly progressive dystonia‐parkinsonism with onset after a head injury due to homozygous pathogenic variants in the FIG4 gene." (PMID 40118803, 2025). "This review aims to explore the association between FIG4 mutations and parkinsonism, with a specific focus on the rare missense mutation p.Ile41Thr (I41T)." (PMID 39457468, 2024). "Two significant gene clusters (clusters 7 and 73) included genes previously associated with Parkinsonism (FIG4 and VAC14) and IBD (IFNAR1, IL6ST, ATG16L1, and NOD2)." (PMID 38741190, 2024). "Our observation that all reported cases of FIG4-related parkinsonism were compound heterozygous for the I41T and a loss-of-function FIG4 mutation highlights such a trend." (PMID 39457468, 2024). "Although the etiologic connection of FIG4 mutations to parkinsonism remains to be confirmed, it seems plausible." (PMID 39457468, 2024). "Here, we present a comprehensive review of reported cases of parkinsonism associated with FIG4 mutations, further expanding the phenotypic heterogeneity attributed to FIG4." (PMID 39457468, 2024). "Notably, all reported cases were compound heterozygous for the I41T variant and a loss-of-function FIG4 mutation, suggesting a potential link between biallelic deficits of FIG4, the I41T mutation, and the development of parkinsonism." (PMID 39457468, 2024). "Our patient extends the phenotypic spectrum of homozygous FIG4‐related neurological disease and the genotypic differential diagnosis of rapid onset dystonia‐parkinsonism." (PMID 40118803, 2025). "First, the small number of identified patients with FIG4-related parkinsonism restricts the ability to draw robust conclusions." (PMID 39457468, 2024). "To date, 12 cases of FIG4-related parkinsonism have been described in the literature, including both PD and atypical parkinsonism." (PMID 39457468, 2024). "To date, no patient with subjacent FIG4 mutations has been reported in the literature as having parkinsonism either in isolation, or in combination with any disorder other than CMT4J." (PMID 39457468, 2024). "No other FIG4 missense mutation, aside from the I41T, has ever been detected in patients with parkinsonism." (PMID 39457468, 2024). "In addition, mutations in the endo-lysosomal trafficking machinery have been implicated in neurodegenerative disorders including ALS and FTD (CHMP2B, FIG4, VAPB, and VCP) and defects in retrograde trafficking increase the risk for Parkinson's disease (VPS35)." (PMID 26357016, 2015). "The syndrome of rapid onset dystonia‐parkinsonism has not been described in association with FIG4 variants, extending the phenotypic spectrum of homozygous FIG4‐related neurological disease and the genotypic differential diagnosis of rapid onset dystonia‐parkinsonism." (PMID 40118803, 2025).
polymicrogyria (4 papers, 2015 to 2021). A developmental brain abnormality characterized by an excessive amount of small convolutions on the surface of the brain and cognitive dysfunction. "Recently, a homozygous missense mutation causing partial loss of FIG4 function was demonstrated to co-segregate with polymicrogyria, psychiatric manifestations and epilepsy in a consanguineous Moroccan family, thus suggesting a role for FIG4 in the regulation of cortical brain development." (PMID 25187576, 2015). "In contrast, patients with (CMT4J) or polymicrogyria retain partial function of FIG4." (PMID 34744978, 2021). "The genes FIG4 and LAMC3 were reported to be highly correlated with the polymicrogyria and cortical malformations, respectively." (PMID 31105557, 2019).
Charcot-Marie-Tooth neuropathy (3 papers, 2011 to 2012). "Loss of the FIG4 phosphatase in humans leads to the autosomal recessive, demyelinating, Charcot-Marie-Tooth neuropathy (CMT), CMT type 4J (OMIM #611228)." (PMID 22912588, 2012). "CMT4J is a severe form of Charcot-Marie-Tooth neuropathy caused by mutation of the phosphoinositide phosphatase FIG4/SAC3." (PMID 21655088, 2011).
lysosomal disorders (3 papers, 2020 to 2023). "There is evidence that a FIG4 dependent signaling pathway is essential for lysosomal function, perhaps independently of its phosphatase function (Bharadwaj, Cunningham, Zhang, & Lloyd, 2016), raising the possibility that the FIG4 associated phenotypes are another type of lysosomal storage disorder." (PMID 32022442, 2020).
motor neuron disease (3 papers, 2012 to 2022). "Among the catalogued ALS-like motor neuron diseases, mutations in SOD1 (ALS1), FUS/TLS (ALS6), VAPB (ALS8), ANG (ALS9), TARDBP (ALS10), FIG4 (ALS11) and a hexanucleotide-repeat expansion (GGGGCC) in the C9ORF72 cause adult onset neurodegenerative disorder." (PMID 22384259, 2012).
Primary lateral sclerosis (3 papers, 2012 to 2023). "Interestingly, an approximately 2% of patients with ALS and primary lateral sclerosis (PLS) carry heterozygous deleterious mutations (nonsynonymous variants) in FIG4, indicating that FIG4 is implicated in the pathogenesis of both peripheral neuropathy and ALS/MNDs." (PMID 22852081, 2012). "FIG4 has a potential role in Charcot–Marie–Tooth disease, ALS, primary lateral sclerosis (PLS), recessively inherited hereditary motor and sensory neuropathy, or Yunis–Varón syndrome." (PMID 37566027, 2023).
Tremor (3 papers, 2020 to 2024). An unintentional, oscillating to-and-fro muscle movement about a joint axis. "Delivery of FIG4 using i.c.v. injection at P1 (postnatal day 1) in the Plt (pale tremor) mouse model with complete loss of FIG4 resulted in a robust amelioration of the central and peripheral neuronal phenotype, which in this model is mainly neuronal." (PMID 38678519, 2024). "The discovery of FIG4 was made by chance when its inactivation through reverse genetics resulted in the “pale tremor mouse model” These FIG4-null mice developed motor symptoms such as tremor, gait difficulties, and abnormal limb postures." (PMID 39457468, 2024).